DDR2 (discoidin domain receptor tyrosine kinase 2)
Diseases named in the same sentence as DDR2 in open-access papers (continued):
Sharing a sentence is not in itself a finding about the gene and the disease.
bladder cancer (5 papers, 2020 to 2024). "DDR2 is critical in bladder cancer progression, affecting proliferation, migration, invasion, metastasis, EMT, and chemotherapy resistance, and its abnormal expression and mutations are linked to aggressive cancer phenotypes, highlighting its potential as a therapeutic target." (PMID 39107713, 2024). "Using two human bladder cancer datasets, CNUH33 and MSKCC34, we identified 18 genes in each dataset whose expression pattern grouped with that of DDR2." (PMID 33247183, 2020). "Moreover, the results of differential relative expression of hub genes, SCD, DDR2, and MT1A, in bladder cancer cells compared to normal urothelial cells from RT-qPCR experiments were consistent with those of DEA on transcriptomic data from the TCGA cohort." (PMID 39107713, 2024). "In a cohort of patients with advanced bladder cancer receiving immunotherapy, we were also able to divide the patients into two molecular subclasses: DDR1 patients with low expression of DDR-related genes and DDR2 patients with high expression of DDR-related genes." (PMID 34335575, 2021).
Hyperglycemia (5 papers, 2019 to 2025). An increased concentration of glucose in the blood. "Further, the present investigations on isolated vascular cells indicated an obligate role for DDR2 in collagen type I gene expression in adventitial fibroblasts and VSMCs exposed in vitro to hyperglycemia, which is an important risk factor associated with metabolic syndrome." (PMID 31805124, 2019). "The upregulation of DDR2—a collagen-binding receptor sensitive to matrix stiffness and hyperglycemia—adds another layer of complexity." (PMID 40426976, 2025). "Gene knockdown and overexpression approaches confirmed an obligate role for DDR2 in hyperglycaemia-induced increase in collagen type I expression in these cells." (PMID 38612393, 2024). "Further, hyperglycaemia was found to increase DDR2 and collagen type I expression in isolated rat vascular adventitial fibroblasts and VSMCs via TGF-β1/SMAD2/3 signalling, which was attenuated by resveratrol." (PMID 38612393, 2024). "Further, in isolated rat vascular adventitial fibroblasts and VSMCs, hyperglycemia increased DDR2 and collagen type I expression via TGF-β1/SMAD2/3, which was attenuated by resveratrol." (PMID 31805124, 2019). "We found that TGF-β1/SMAD2/3 signaling mediates the stimulatory effect of hyperglycemia on DDR2 that in turn enhances collagen type 1 expression via ERK1/2 MAPK activation." (PMID 31805124, 2019). "Such a postulation is supported by our observations that resveratrol abolishes the stimulatory effect of hyperglycemia on DDR2 and collagen in isolated adventitial fibroblasts and VSMCs." (PMID 31805124, 2019). "Notably, gene knockdown and overexpression approaches demonstrated an obligate role for DDR2 in hyperglycemia-induced increase in collagen type I expression in these cells." (PMID 31805124, 2019). "Metformin was found to attenuate hyperglycaemia-induced increase in DDR2 mRNA and protein expression by inhibiting TGF-β1/SMAD2/3 signalling that mediates the stimulatory effect of hyperglycaemia on DDR2 expression." (PMID 36614028, 2022). "In actual fact, we observed that the Sca1+ population was significantly reduced in CSCs after 7 days of hyperglycemia, with respect to normoglycemia, as well as the Sca1+/CD90+/DDR2- fraction." (PMID 35365624, 2022). "We demonstrate for the first time that metformin prevents hyperglycaemia-induced increase in DDR2 expression in vascular adventitial fibroblasts by inhibiting the TGF-β1/SMAD2/3 signalling pathway, which enhances DDR2 expression in response to hyperglycaemia." (PMID 36614028, 2022).
lymph node metastasis (5 papers, 2015 to 2024). "Concerning DDR2, a high expression was associated with higher frequencies of T4, lymph node metastasis, peritoneal spread, and worse prognosis, suggesting that DDR2 expression might be an effective therapeutic target." (PMID 32426274, 2020). "In CRC, high DDR2 expression was associated with higher frequencies of T4, lymph node metastasis, peritoneal spread, and poorer prognosis compared to low DDR2 expression, suggesting that DDR2 expression might be an effective therapeutic target." (PMID 31641356, 2019). "In the univariate analysis, DDR2 status (p = 0.0019) as well as pT (p < 0.0001), lymph node metastasis (p = 0.032), histological grade (p = 0.032), ER (p = 0.012), PR (p = 0.0006), and Ki67 LI (p = 0.0002) were demonstrated as significant prognosis factors." (PMID 39766183, 2024). "It is likely that continuous DDR2 expression, which is related to stromal beclin-1 expression, plays a role in local recurrence and lymph node metastasis." (PMID 25955408, 2015). "Lastly, the presence of lymph node metastasis correlated with elevated risk scores and DDR2 expression but not with SCD and MT1A." (PMID 39107713, 2024).
ovarian tumor (5 papers, 2022 to 2026). "DDR2 can confer protection against ferroptosis in ovarian tumor-associated fibroblasts (CAFs) by regulating the xCT–GSH–GPX4 antioxidant pathway and cellular iron metabolism." (PMID 41492134, 2026). "In sum, these data indicated that the presence of DDR2 in omental ovarian tumor CAFs controlled polyamine production, likely through DDR2-regulated Arginase-1 production." (PMID 37996700, 2024). "In conclusion, our work uncovered that DDR2 signals can regulate collagen protein synthesis and secretion by CAFs from human and mouse ovarian tumors." (PMID 37996700, 2024). "Media secreted by Ddr2-depleted human ovarian tumor CAFs leads to decreased ovarian tumor cell invasion and migration compared to media secreted by Ddr2-expressing CAFs." (PMID 37996700, 2024). "We have previously shown that high stromal expression of DDR2 protein in human ovarian tumors correlates with worse overall survival." (PMID 37996700, 2024). "Notably, LPA activates PI3K/Akt/mTOR/hypoxia-inducible factor 1α (HIF1α) signalling that drives discoidin domain receptor 2 (DDR2) expression to subsequently promote ovarian tumour cell invasion." (PMID 38607068, 2024). "DDR2-dependent arginase activity in CAFs appeared to be critical for collagen deposition in ovarian tumors and could explain how DDR2 regulates tumor ECM fibrillar collagen production and mechanical properties." (PMID 37996700, 2024). "Furthermore, DDR2-depleted and POSTN-overexpressing CAFs co-injected with ovarian tumor cells had increased tumor burden compared to mice injected with tumor cells and DDR2 and POSTN-depleted CAFs." (PMID 35884543, 2022). "Thus, targeting stromal DDR2 may enhance ferroptosis sensitivity and improve ovarian tumor responses to PARPi therapy." (PMID 41492134, 2026). "To determine if DDR2-dependent (Arg1-dependent) polyamine production specifically could contribute to ovarian tumor cell invasion, we added exogenous spermidine or putrescine to CM from Ddr2-depleted CAFs and repeated the Boyden-chamber Matrigel invasion assays." (PMID 37996700, 2024). "COL11A1 suppressed CDDP-induced apoptosis in ovarian tumor cells by promoting apoptosis inhibitor proteins such as BIRC2, BIRC3, and XIAP via discoidin domain receptor 2 (DDR2)-Src-PI3K/Akt-NF-kB axis through α1β1 integrin." (PMID 38741195, 2024). "To determine if DDR2 regulates Arg1 expression and arginase activity in omental CAFs in vivo, we made use of CAFs from the mouse ID8TB−/− syngeneic ovarian tumor model." (PMID 37996700, 2024). "In human ovarian tumor CAFs, SNAIL protein was detected at the promoter region of the human Arg1 gene, while in Ddr2-depleted CAFs, there was less SNAIL detected." (PMID 37996700, 2024).
Arthritis (4 papers, 2011 to 2021). Inflammation of a joint. "Discoidin domain receptor 2 (DDR2) is a tyrosine kinase receptor for fibrillar collagen expressed during pathologic scarring, for example wound healing, arthritis and cancer." (PMID 21288331, 2011). "Although imatinib is not a selective inhibitor for DDRs, it is possible that inhibition of DDR2 by imatinib contributes to the suppressive effect in arthritis development, and DDR2-selective inhibition may be a potential novel therapeutic strategy for RA therapy in the future." (PMID 28270508, 2017).
dwarfism (4 papers, 2013 to 2023). "DDR2 functions in endochondral bone formation likely explain the dwarf phenotype, reduced A-P skull length and shortened snout of Ddr2 deficient mice and as well as the dwarfism and the depressed facial features of SMED, SL-AC patients." (PMID 36656123, 2023). "Deletions of DDR2 in mice and humans have been found to be associated with dwarfism and short limbs." (PMID 25658585, 2015). "Mutations in the human DDR2 gene cause a rare form of dwarfism, spondylo-meta-epiphyseal dysplasia short limb-hand type." (PMID 23128141, 2013). "The impaired skeletal growth in Ddr2−/− mice is due to reduction in chondrocyte proliferation and mirrored by a rare form of dwarfism in humans resulting from mutations in the DDR2 gene, termed spondylo-meta-epiphyseal dysplasia short limb-hand type." (PMID 23128141, 2013). "Knockout of DDR2 in mice leads to dwarfism, manifested by shortening of long bones." (PMID 25658585, 2015). "Of the identified genes associated with cell adhesion, DDR2 encoding discoidin domain receptor 2, a collagen receptor, regulates cell proliferation, and the absence of DDR2 results in dwarfism in mouse mutants." (PMID 36836780, 2023).
liposarcoma (4 papers, 2014 to 2024). A usually painless malignant tumor that arises from adipose tissue. "In conclusion, this work is the first to report the entire genome of a well-differentiated liposarcoma with novel chromosomal rearrangements associated with amplification of therapeutically targetable genes such as MDM2 and DDR2." (PMID 24505276, 2014). "Further study of these findings in a larger cohort of liposarcoma patients is warranted to estimate the true prevalence of therapeutic targets such as DDR2 and to advance the understanding of the genetic basis of liposarcoma." (PMID 24505276, 2014). "Receptor tyrosine kinase (RTK) genes DDR2 (discoidin domain receptor tyrosine kinase 2), ERBB3 (Erb-B2 receptor tyrosine kinase 3), FGFR1 (fibroblast growth factor receptor 1), and ROS1 (ROS Proto-Oncogene 1) are also amplified in dedifferentiated liposarcoma." (PMID 33498189, 2021). "Although the case showed MDM2, CDK4, and DDR2 gene amplification, which were genetically similar to liposarcoma, upon microscopic examination, neither the primary nor the recurrent IMTs presented as liposarcoma." (PMID 32195970, 2020). "While these studies suggest DDR2 may play an important role in liposarcoma, its precise role remains to be elucidated through characterization of additional patients with WDLS and by correlating clinical phenotypes with DDR2 status." (PMID 24505276, 2014). "Interestingly, a potential gene fusion was also identified in amplified DDR2, which is a potential therapeutic target of kinase inhibitors such as dastinib, that are not routinely used in the treatment of patients with liposarcoma." (PMID 24505276, 2014).
liver cancer (4 papers, 2020 to 2024). An epithelial or non-epithelial malignant neoplasm that arises from the liver. "However, long non-coding RNA CEBPA-DT, a divergent transcript of CEBPA, has recently been found to promote liver cancer metastasis through DDR2/β-catenin activation." (PMID 38442712, 2024). "By analyzing RNA-seq data from TCGA and GTEx, we discovered that ATF3, ACSL1, LPIN1, and DDR2 were significantly downregulated while DDIT3 was upregulated in liver tumor compared with normal tissues, implying that these five genes might be associated with liver cancer." (PMID 37580343, 2023).
sarcoma (4 papers, 2014 to 2025). A usually aggressive malignant neoplasm of the soft tissue or bone. "As for cell proliferation, we then analyzed the activation of DDR2 in A204 sarcoma cells in collagen 3D matrices." (PMID 27121132, 2016).
fibrosis (3 papers, 2017 to 2025). the formation of excess fibrous connective tissue in an organ or tissue in a reparative or reactive process. "Interestingly, DDR2 has been implicated as a key regulator in cardiac fibrosis." (PMID 40468620, 2025). "Here, we tested the hypothesis that Discoidin Domain Receptor 2 (DDR2), a collagen-specific receptor tyrosine kinase, is a determinant of arterial fibrosis." (PMID 31805124, 2019).
glioma (3 papers, 2016 to 2022). A benign or malignant brain and spinal cord tumor that arises from glial cells (astrocytes, oligodendrocytes, ependymal cells). "RMPAhigh gliomas were also enriched in the expression of ERBB2, FGFR1 and MET (and its ligand HGF), DDR2 (a receptor for activated collagen fibers), as well as the WNT co-receptors ROR1 and RYK." (PMID 27385209, 2016).
Infertility (3 papers, 2015 to 2025). "Silencing the DDR2 resulted in decreased chromatin maintenance, disturbed hormonal signaling pathways in ovarian granulosa cells, blocked ovulation, and infertility." (PMID 35346019, 2022). "The intensity of Ddr2 immunoreactivity in the infertile testes was much lower than that in control testes." (PMID 26158267, 2015). "By targeting DDR2, it may be possible to not only inhibit ECM remodeling and cell migration but also modulate the inflammatory responses that drive chronic pain and infertility in endometriosis patients." (PMID 41424583, 2025).
invasive breast carcinoma (3 papers, 2016 to 2024). A carcinoma that infiltrates the breast parenchyma. "This compensatory mechanism has been previously reported in invasive breast carcinoma from patients in which DDR1 and DDR2 were coordinately and inversely deregulated." (PMID 31130862, 2019).
metabolic syndrome (3 papers, 2019 to 2024). A cluster of metabolic risk factors for CARDIOVASCULAR DISEASES and TYPE 2 DIABETES MELLITUS. "In contrast to these reports, our findings from both the in vitro and in vivo models point to a positive correlation between DDR2 and collagen expression and remodeling, suggestive of a role for DDR2 in promoting arterial fibrosis associated with metabolic syndrome." (PMID 31805124, 2019). "In summary, the findings from this study support a role for DDR2 in the pathogenesis of vascular fibrosis in a setting of metabolic syndrome." (PMID 31805124, 2019). "Together, our observations point to DDR2 as a hitherto unrecognized molecular link between metabolic syndrome and arterial fibrosis, and hence a therapeutic target." (PMID 31805124, 2019). "The observations suggest that DDR2 may act as a molecular link between metabolic syndrome and arterial fibrosis, which would make it a potential therapeutic target." (PMID 38612393, 2024). "Further, our recent studies provide robust evidence that DDR2 may be a molecular link between arterial fibrosis and metabolic syndrome in rhesus monkeys." (PMID 36614028, 2022). "Recently, it was found that augmented expression of DDR2 within adventitial fibroblasts and VSMCs correlates with increased deposition and remodelling of collagen within the medial and adventitial layers of the abdominal aorta in a rhesus monkey model of metabolic syndrome." (PMID 38612393, 2024). "Notably, the increase in collagen deposition and adverse ECM remodeling correlated well with increased expression of DDR2 within adventitial fibroblasts and VSMCs in the HFS-fed group, suggesting a possible link between DDR2 and collagen production in a setting of metabolic syndrome." (PMID 31805124, 2019).
metastasis (3 papers, 2015 to 2020). The spread or migration of cancer cells from one part of the body (where they first appeared) to another. "Especially FGFR1 (13% in PTvs.N and 7% in Mvs.PT to 10% in AMP), FGFR3 (7% in PTvs.N and Mvs.PT to 2% in AMP), DDR2 in lymph node metastasis (13% in Mvs.PT to 3% in AMP) and MET (7% in PTvs.N and Mvs.PT to 2% AMP, FC 2.4) seem to be similarly overexpressed." (PMID 29743718, 2018).
osteoporosis (3 papers, 2015 to 2023). A condition of reduced bone mass, with decreased cortical thickness and a decrease in the number and size of the trabeculae of cancellous bone (but normal chemical composition), resulting in increased fracture incidence. "Although this preliminary finding suggests that certain polymorphisms in DDR2 may be risk factors for osteoporosis, more studies are needed, particularly in diverse populations to assess the significance of these findings." (PMID 38222874, 2023). "Considering the biological function of DDR2, we suggest that DDR2 could be a new candidate in determining the risk of osteoporosis and fractures." (PMID 25658585, 2015). "Collectively, our results reveal a novel role of Ddr2 in fat-bone crosstalk, and providing a potential therapeutic strategy for obesity and osteoporosis." (PMID 34645939, 2022). "Furthermore, adenovirus-mediated overexpression of Ddr2 in the femur marrow cavity partially reversed osteoporosis in ovariectomized mice, a phenotype that is largely due to osteoclast activation." (PMID 38222874, 2023). "Whether DDR2 could be exploited as a novel therapeutic agent for osteoporosis warrants further investigation." (PMID 25658585, 2015). "Our findings, together with the prior biological evidence, suggest that DDR2 could be a new candidate for osteoporosis in Chinese population." (PMID 25658585, 2015). "Given the biological function of DDR2 involved in bone, it is reasonable to hypothesize that DDR2 may influence BMD and could be a new candidate gene for osteoporosis risk estimation, but the genetic variations actually leading to the association remain to be elucidated." (PMID 25658585, 2015). "DDR2 gene, playing an essential role in regulating osteoblast differentiation and chondrocyte maturation, may influence bone mineral density (BMD) and osteoporosis, but the genetic variations actually leading to the association remain to be elucidated." (PMID 25658585, 2015).
rheumatoid arthritis (3 papers, 2016 to 2024). A chronic, systemic autoimmune disorder characterized by inflammation in the synovial membranes and articular surfaces. "Area under the ROC curve (AUC) value greater than 0.8 was considered as a condition for good diagnostic value, and DDR2 and LOXL1 performed well in distinguishing normal and rheumatoid arthritis samples." (PMID 38217541, 2024). "Therefore, we investigated the ratio of LOXL1 and DDR2 to different immune cell infiltrations between rheumatoid arthritis and normal samples, aiming to determine the association between the infiltration status of immune cells and the expression levels of LOXL1 and DDR2." (PMID 38217541, 2024). "Our findings suggested that DDR2 and LOXL1 may be involved in the progression of rheumatoid arthritis by influencing the activities of multiple immune cells." (PMID 38217541, 2024).
triple-negative breast carcinoma (3 papers, 2022 to 2026). An invasive breast carcinoma which is negative for expression of estrogen receptor (ER), progesterone receptor (PR), and human epidermal growth factor receptor 2 (HER2). "In metastatic triple-negative breast cancer (TNBC), DDR2 is highly expressed along with the EMT inducer MMP14." (PMID 41492134, 2026). "Further analysis identified DDR2 as the most upregulated receptor tyrosine kinase and a shared downstream effector of FOXQ1 and SNAI1 in triple-negative breast cancer (TNBC) cell lines." (PMID 36713812, 2022).
Warburg-Cinotti syndrome (3 papers, 2022 to 2025). "Warburg-Cinotti syndrome is an autosomal dominant condition caused by the DDR2 variants DDR2-L610P or DDR2-Y740C." (PMID 41259339, 2025). "The Warburg-Cinotti syndrome-related missense variants (p.L610P and p.Y740C) affect conserved residues in the DDR2 TKD." (PMID 41259339, 2025). "Activating mutation of DDR2 causes Warburg-Cinotti Syndrome, in which wasting subcutaneous tissue and acro-osteolysis are observed." (PMID 34645939, 2022). "Warburg-Cinotti syndrome (WCS) is a rare disorder caused by mutations in the DDR2 gene." (PMID 41778429, 2025).